RN7SL731P (RNA, 7SL, cytoplasmic 731, pseudogene)
Gene: Miscellaneous RNA gene on chromosome 1 (10,306,465 to 10,306,757, forward strand). Ensembl gene ENSG00000264501.
Homologues: Orthologues: chimpanzee Metazoa_SRP (98% identical), macaque Metazoa_SRP (93% identical), dog Metazoa_SRP (71% identical), mouse Gm55851 (57% identical). Paralogues in human: RN7SL1 (80% identical), RN7SL2 (80% identical), RN7SL3 (80% identical), RN7SL126P (80% identical), RN7SL378P (79% identical), RN7SL301P (78% identical), RN7SL664P (78% identical), RN7SL147P (78% identical), RN7SL218P (78% identical), RN7SL597P (78% identical), RN7SL856P (78% identical), RN7SL44P (77% identical), and 701 more.